MMP9 (matrix metallopeptidase 9)
Diseases named in the same sentence as MMP9 in open-access papers (continued):
Sharing a sentence is not in itself a finding about the gene and the disease.
breast carcinoma (continued). "Finally, to show that the WNT‐5A‐induced inhibition of MDA‐MB468 breast cancer cell migration is dependent on reduced MMP9 activity, we studied MDA‐MB468‐5A cell migration in the absence and presence of active human recombinant MMP9." (PMID 23727359, 2013). "The specificity of AM9D toward MMP9 mRNA was demonstrated in MDA-MB-231 human breast cancer cells." (PMID 23407024, 2013). "In addition, higher MMP-9 protein concentration was detected in breast cancer tissue when compared to normal breast tissue." (PMID 23874773, 2013). "In addition, SAHA inhibited the migration and invasion abilities of 4T1 cells and inhibited breast cancer cell migration by inhibiting the activity of MMP-9." (PMID 24130769, 2013). "Furthermore, Twist protein expression correlated with MMP-2 and MMP-9 protein expression in the breast cancer tissue specimens." (PMID 23935727, 2013). "However, no other prior studies have examined the relationship between the circulating level of lipocalin-2 and MMP-9 and their combined effects on the prognosis of breast cancer." (PMID 22640376, 2012). "Insulin stimulation increased MMP-9 levels, demonstrating that insulin may also enhance cell signaling pathways which lead to metastasis from the site of primary tumors in breast cancer." (PMID 22226054, 2012). "Whether breast cancer cells that express ABCC5, and thus maintain low cytoplasmic cGMP levels through active efflux, are associated with elevated MMP-9 expression or secretion requires further investigation." (PMID 23174366, 2012). "Although the details of the mechanism by which endogenous β-arrestins regulate MMP activity is currently unknown, β-arrestins can scaffold Src, shown previously to promote invasion via MMP-9 secretion in breast cancer cells." (PMID 21738726, 2011). "To this end, we used HRG-β1 to transactivate HER2 signaling and investigated whether pterostilbene inhibits HER2-mediated invasion, metastasis and MMP-9 expression of breast carcinoma." (PMID 19617202, 2011). "Our previous study showed that MMP9 was upregulated in breast cancer." (PMID 21266059, 2011). "In addition, estrogen has been shown to regulate the activity of MMP-2 and MMP-9 in ER+ breast cancer cells and a positive correlation between ER-α expression and the effects of estrogen on MMP gene expression in breast cancer cells." (PMID 21267453, 2011). "Taken together, our present results suggest that pterostilbene may serve as a chemopreventive agent to inhibit HRG-β1/HER2-mediated aggressive and invasive phenotype of breast carcinoma through down-regulation of MMP-9, p38 kinase and Akt activation." (PMID 19617202, 2011). "One member of this family, MMP-9 was up-regulation in invasive cancers, including breast cancer." (PMID 21595884, 2011). "Taken together, these effects could be related to the down-regulation of MMP-9 in breast carcinoma cells by UTI." (PMID 21345194, 2011). "On basis of these studies, it is suggested that MMP-9 may be a valuable target of therapeutic intervention in breast cancer patients whose HER2 are overexpressed." (PMID 19617202, 2011). "Taken together, our results suggest that cholesterol levels in lipid rafts are critical for the migration, invasion, and angiogenesis of breast carcinoma cells and could be a critical regulatory factor in these cancer cell processes mediated by uPAR and MMP-9." (PMID 21106094, 2010). "Whether serum levels of MMP-9, NGAL and their complex can reflect the relative risk of patients with benign diseases for developing breast cancer remains to be investigated in future studies." (PMID 19889214, 2009). "In addition, BER significantly suppresses cell migration and invasion, as well as decreases pro-MMP-9/pro-MMP-2 activation in breast cancer cells." (PMID 19796390, 2009).
breast carcinoma (continued). "Kalembeyi and colleagues demonstrated up-regulation of MMP-9 expression in mouse mammary carcinoma cells in response to exogenous TNC, while a recent study reported that the invasion-promoting effect of TNC on glioma cells is mediated through up-regulation of MMP-12." (PMID 19405959, 2009). "Furthermore MMP-9, -11 and -28 mRNA expression was higher in breast cancer tissue grade 3 than in normal breast tissue." (PMID 19531263, 2009). "Elevated levels of tumour-derived MMP-9 and mononuclear inflammatory cell-derived MMP-1/MMP-7/MMP-9/MMP-11/MMP-13/MMP-14 are significantly associated with higher rates of distant metastases in breast cancer." (PMID 19014637, 2008). "Neutrophil gelatinase-associated lipocalin–matrix metalloproteinase-9 (MMP-9) complexes were identified in nearly 84% of urine sample from breast cancer patients while being absent from matched control samples." (PMID 18392050, 2008). "Furthermore, selective antagonists for MMP-2/MMP-9 or MMP-3 also suppressed the stimulatory effect of IL-17 on breast cancer invasion, although to a lesser extent than GM6001." (PMID 19014637, 2008). "In those MMPs, MMP-9 (92 kDa gelatinase) is particularly known to play a critical role in cancer progress, such as angiogenesis as well as tumor growth, invasion and distant metastasis of various tumors and breast cancer as well." (PMID 19052522, 2008). "It has been reported that IGF-1 upregulates MMP-9 in breast cancer cells." (PMID 14997210, 2004). "This is in accord with earlier findings that the expression of pro-MMP-9 and the microvascular density may be related in human breast carcinoma." (PMID 14710236, 2004). "Indeed, an increase in MMP-9 secretion has been shown to enhance the invasive capacities of breast cancer cells." (PMID 12698185, 2003). "The incubation of the breast-cancer-derived MDA-MB231 cells with monocytes resulted in an increase in factors involved in cell invasion (i.e. both cancer cells and monocytes-associated urokinase and Tissue Factor, and PAI-1 and MMP-9 secretion)." (PMID 12698185, 2003). "However, there was also a study indicating that BMAL1 could promote breast cancer cell invasion and metastasis by up-regulating MMP9 expression through the activation of the NF-κB signaling pathway." (PMID 40046513, 2025). "In murine breast cancer models, DCs stimulated with leptin (particularly when combined with LPS) reduced tumor-promoting gene expression, including matrix metalloproteinase 9 (MMP9), CCL5, and vascular endothelial growth factor (VEGF), and decreased IL-6 secretion." (PMID 41516046, 2025). "In addition to breast carcinomas, several other types of cancer, such as oral cancer, retinoblastoma, bladder cancer, and ovarian epithelial cancer, have been associated with MMP2 and MMP9 overexpression." (PMID 40735254, 2025). "Studies have shown that MMP9 is upregulated in breast cancer, where it correlates with poor patient survival outcomes, suggesting that its expression might facilitate tumor invasion and metastasis by remodeling the ECM to create pathways for cancer cell dissemination." (PMID 41259376, 2025). "Additionally, MMP-9 and VEGF-C expression were significantly associated with lymph node status, highlighting their potential as valuable diagnostic marker for lymph node metastasis in patients with breast cancer." (PMID 40266038, 2025). "Moreover, SIRT6 promoted breast cancer metastasis by upregulating matrix metalloproteinase-9 (MMP-9) through the MAPK, NF-κB, and AP-1 pathways; silencing SIRT6 reduced cell invasion and migration in MCF-7 and MDA-MB-231 cells, suggesting its direct role in metastatic progression." (PMID 41471349, 2025). "Higher circulating levels of PGLYRP1, CAMP, MMP9 and CEACAM8 prior to and after the first dose of DOX chemotherapy may further contribute to progressive cardiovascular disorders in breast cancer survivors and may potentially predict the risk of both acute subclinical and late cardiotoxicity." (PMID 39273682, 2024).
breast carcinoma (continued). "Furthermore, EVs isolated from the adipocytes of obese patients, enriched in leptin and MMP9, could promote the release of MMP9 by breast cancer cells." (PMID 39697630, 2024). "Thus, we believe that the differential expression of GATA4 across various breast cancer cell lines, and its regulated expression of MMP9, could contribute to intratumor heterogeneity." (PMID 38653973, 2024). "Therefore, we hypothesized that lidocaine (combined with sevoflurane or propofol anesthesia) during breast cancer surgery inhibits the expression of biomarkers associated with metastasis and recurrence (specifically H3Cit, NE, MPO, MMP-9 and VEGF-A)." (PMID 38678209, 2024). "In breast cancer cells, mature adipocytes induce the EMT phenotype and promote cancer cell migration, invasion and proliferation, which could be associated with the upregulation of MMP-9 and twist-related protein 1 (TWIST1)." (PMID 36670988, 2023). "Conversely, the reduction in Snail1, Vimentin and MMP-9 expression as well as the increase in E-cadherin expression in the MCF-7-liposome-si-CD147 group indicate that targeting CD147 could potentially reverse EMT in breast cancer cells." (PMID 38066486, 2023). "In a spontaneous murine breast cancer model, pre-metastatic lung tissue experienced an influx of immature myeloid cells, which subsequently remodeled the endothelium via matrix metalloproteinase 9 (MMP9) and promoted metastasis—a phenotype that could be reverted via MMP9 deletion." (PMID 37373202, 2023). "Therefore, the mechanism causing breast cancer cell adhesion, migration, and invasion can be explained by SIPA1, which may be achieved by regulating the ITGB1/FAK/Akt-MMP9 signaling pathway." (PMID 36230738, 2022). "In our study, two pairs of HER2-positive breast cancer and one pair of TNBC samples were used for RNA-sequencing and further analyses revealed that MMP9 was one of the most up-regulated expressed mRNA and may promote breast cancer progression by regulating fatty acid metabolism." (PMID 35852149, 2022). "Therefore, MMP-9 expression has been extensively used as a marker for breast cancer metastasis." (PMID 35840633, 2022). "Importantly, MMP9 protein is constitutively expressed by breast cancer cell lines (MDA-MB-231)." (PMID 36293492, 2022). "And their cross-talk regulates hypoxia/reoxygenation (H/R) induces breast cancer progression and further regulates the expression of melanoma cell adhesion molecule (MelCAM) urokinase-type plasminogen activator (uPA) matrix metalloproteinase-9 (MMP-9) and VEGF." (PMID 36226050, 2022). "However, MMP9 expression varies among the molecular subtypes of breast carcinoma." (PMID 35719919, 2022). "Studies have demonstrated that TNFRSF12A is highly expressed in breast cancer, and a high TNFRSF12A level associated with matrix metalloproteinase (MMP)-9 overexpression is related to cancer progression; thus, TNFRSF12A-targeting therapy could improve survival rates in cancer." (PMID 34917619, 2021). "Furthermore, survival analysis showed that MMP9 has a significant relationship with prognosis in breast cancer patients and could thus represent a prognostic biomarker for breast cancer." (PMID 33854593, 2021). "Therefore, the study on the transcription of MMP9 may provide a possibility for revealing the fine regulation of MMP9 and finding a novel therapeutic target for breast cancer." (PMID 34772908, 2021). "Therefore, we wanted to investigate how reduced MMP-9 expression affects the response of breast cancer cells (MDA-MB-231 and MCF-7) to CP treatment and whether there is a correlation between MMP-9 and CK19." (PMID 34884588, 2021). "Therefore, we speculate that BRD4 may be involved in breast cancer brain metastasis by upregulating MMP9, resulting in BBB disruption, and thereby promoting the initiation and progression of brain metastasis." (PMID 34421353, 2021).
breast carcinoma (continued). "Interestingly, reduced levels of fibulin-5 in breast cancer have been reported to be required for metastasis formation in the liver and lung by suppressing the activity of MMP9, a protease that remodels the ECM during metastatic niche formation and promotes metastatic outgrowth." (PMID 33836007, 2021). "Moreover, we decided to check whether CP, a cytostatic commonly used in breast cancer, may intensify the changes observed after MMP-9 silencing or abolish it." (PMID 34884588, 2021). "In contrast to constitutively expressed MMP-2, MMP-9 is inducible, and represents one of the most important proteinases that mediates tumor progression in human lung cancer, gliomas, pancreatic cancer, head and neck cancer, prostate cancer, gastric cancer, and breast cancer." (PMID 34769032, 2021). "In this study, we identified that TIMELESS may repress the invasion and metastasis of breast cancer cells via inhibiting the acetylation of p65, inhibiting the activation of NF-κB, thus down-regulating the expression of MMP9, and then inhibiting the invasion and metastasis of breast cancer cells." (PMID 33430865, 2021). "Upregulation of Sp7 in breast cancer cells is associated with increased invasion and bone metastasis, and this may occur by upregulation of ECM modifying metalloproteinases, MMP9 and MMP13, and other factors that increase vascularization, and affect bone cell function." (PMID 32755539, 2020). "Therefore, we sought to evaluate in the current study whether ML could modulate the metastasis-related factors, IL-8 and MMP-9, to regulate the migration and invasion of breast cancer cells." (PMID 31893611, 2020). "Furthermore, we found that silencing of KIF3B decreased the expression of Dvl2, phospho-GSK-3β, total and nucleus β-catenin, then subsequent down-regulation of Wnt/β-catenin signaling target genes such as CyclinD1, C-myc, MMP-2, MMP-7 and MMP-9 in breast cancer cells." (PMID 33542902, 2020). "This compound could inhibit invasiveness of breast cancer by decreasing MMP-9 expression." (PMID 32458624, 2020). "Furthermore, oncogene-driven hyperactive Raf/MEK/ERK signaling induces MMP9 expression in breast cancer cells, suggesting that oncogenic features of the cancer cells may accelerate ECM remodeling-dependent mechanisms of reawakening." (PMID 33014869, 2020). "Matrix metalloproteinase-2 (MMP-2) and MMP-9 have been suggested to promote the invasion of breast cancer cells and we thus reasoned that these factors could be mediators of the invasive potential of breast cancer cells through IL-22." (PMID 31935914, 2020). "In particular, it has been reported that non-toxic doses of 15d-PGJ2, DHA, and troglitazone reduce breast cancer cell invasion through the downregulation of the matrix metalloproteinases-9 (MMP9), a protease implicated in the extracellular matrix degradation in MCF-7 breast cancer cells." (PMID 32937951, 2020). "Altogether, these data suggest that a decreased expression of Gal-3 during breast cancer progression might render tumor cells less adherent and more migratory by regulating the expression of tumor GAGs and MMP9, thus increasing the metastatic potential of the tumor." (PMID 31949431, 2019). "The inhibitor for TGF‐β1 receptor in this study sufficiently reverses the TGF‐β‐ and/or MMP‐9 induced the increased invasive abilities of the breast cell lines supplies further evidences supporting that TGF‐β/SMAD signalling increases malignancy of the cultured breast cancer cells." (PMID 31264317, 2019). "Finally, we demonstrated that BMAL1 could promote the invasiveness of breast cancer cells by up-regulating the expression and activity of MMP9." (PMID 31346317, 2019). "We focused on the clinical relevance of ENO1 and MMPs (MMP-2 and MMP-9) overexpression in breast cancer tissues: The association between the higher ENO1, MMP-2 and MMP-9 expression with a worse prognosis suggest that the elevated ENO1 and MMPs expression are promising biomarkers for breast cancer." (PMID 31416219, 2019).
breast carcinoma (continued). "Quercetin-3-O-glucuronide was also reported as an active compound which could inhibit intracellular reactive oxygen species in mouse fibroblast 3T3 cells induced by H2O2 attack and suppress invasion of MDA-MB-231 breast cancer cells and matrix metalloproteinase 9 (MMP-9) induction." (PMID 31249524, 2019). "Therefore, CAPE-pNO2 against the growth and metastasis of breast cancer might be via restraining MMP-2, MMP-9, and VEGFA expression, and these proteins were associated with the EGFR/STAT3/Akt signaling pathway." (PMID 31214503, 2019). "BTG1 expression was down-regulated in breast cancer cells and significantly correlated with proliferation, poor overall survival, histological grade, clinic stage, and lymph node metastasis by regulating protein expression levels of Cyclin-D1, Bcl-2, and MMP-9." (PMID 29416786, 2018). "Previous studies have shown that the IL-17A-mediated invasion of breast cancer cells can be inhibited by selective antagonists of the matrix metalloproteinase 9 (MMP-9), suggesting that the cross-talk between IL-17A and MMP-9 may promote cancer invasiveness and metastasis." (PMID 29983876, 2018). "In addition, IL-17A-dependent invasion of breast cancer cells can be inhibited by MMP-9 inhibitors." (PMID 29983876, 2018). "After adjusting for oral contraceptive use and family history of breast cancer, the presence of the T allele and the TT (TC + TT) genotype of the MMP-9 polymorphism was not directly associated with tumor occurrence (OR = 1.159, 95%CI: 0.6625–1.997, p = 0.5964)." (PMID 30352460, 2018). "In the TME, MMP9 may also be produced by fibroblasts or breast carcinoma cells." (PMID 28423685, 2017). "From our results we conclude that TNF-α-induced activation of the MAPK/ERK signaling pathway may promote breast cancer cell migration via both upregulation of MMP9, CD26 and FAP-α and concentration of these proteases, as also MT1-MMP and MMP2, in the lipid rafts." (PMID 27042827, 2016). "It should be taken into consideration that several studies have reported that HO-1 activation prevents breast cancer proliferation and prostate cancer angiogenesis and mediates the anticancer activity of some drugs such as andrographolide by reducing the MMP-9 expression in breast cancer cells." (PMID 26697129, 2016). "Moreover, magnolol inhibits breast cancer invasiveness by suppressing MMP-9 expression." (PMID 26423775, 2015). "In addition, interaction with breast cancer cells induced MMP-9 and arginase-1." (PMID 26078009, 2015). "In addition, we investigated whether the Ras/Raf/ERK signaling pathway and MMP-9 played crucial roles in the promotion of growth and invasiveness of breast cancer cells mediated by EpCAM." (PMID 26356670, 2015). "Furthermore, we found that some breast cancer diagnosis-associated features such as tumor size, tumor grade, estrogen receptors (ER) and progesterone receptors (PR) levels, were correlated well with TSP50/p65 and TSP50/MMP9 expression status." (PMID 25811800, 2015). "As an example, MMP-9 is elevated in breast cancer patients, including tumor cells; additionally, serum, plasma, and urine may be also useful for early cancer diagnosis and metastasis prediction, and MMP-13 correlates with aggressiveness of the tumor and poor prognosis in HER2-positive tumors." (PMID 26404249, 2015). "Thus, early and exact detection of the expression level of MMP-9 may provide effective introductions for the prognostic therapy of MMP-9 positive breast cancer patients." (PMID 26270045, 2015). "Importantly, our results suggest a potentially significant correlation of TSP50 and MMP9 in the metastatic progression of human breast cancer, therefore, TSP50 may represent a novel favorable intervention target against breast cancer metastasis." (PMID 25811800, 2015).